LEP (leptin)
Diseases named in the same sentence as LEP in open-access papers (continued):
Sharing a sentence is not in itself a finding about the gene and the disease.
Obesity (continued). "Mutations of the leptin gene result in severe obesity as well as impaired thermogenesis and lipolysis, whereas leptin treatment reduces food intake and rapidly depletes adipose mass, mainly WAT." (PMID 34439626, 2021). "Elevated leptin levels are associated with craving in addictive behaviors, as well as with food cue–induced brain activations in individuals with obesity." (PMID 34173157, 2021). "Leptin, a hormone associated with obesity that is known to play a catabolic role in articular cartilage, especially in women, was significantly increased in the late-stage PTOA group compared to the control group." (PMID 33671471, 2021). "Monogenic obesity results from highly infrequent single genes mutations (such as LEP, POMC); however, some of them also demonstrated an association with polygenic obesity (e.g., MC4R, FTO)." (PMID 34445769, 2021). "This review summarizes possible mechanisms that connect obesity with SLE, including a vitamin D deficiency and an increase in adipokines, such as leptin and adiponectin, all of which are frequently observed in individuals with obesity and patients with SLE." (PMID 33557015, 2021). "A single-nucleotide polymorphism identified in the 5’-untranslated region of the leptin gene (LEP -2548 G/A polymorphism) and its association with obesity is the most studied in humans." (PMID 34084149, 2021). "Although leptin levels are not correlated with sleeping/waking regimes, sleep disorders related to obesity, such as sleep apnea, appear to be associated with increases in leptin levels." (PMID 34884416, 2021). "The majority of circulating leptin is produced in adipose tissue, with leptin mRNA levels normally being directly correlated with adipocyte size, and high circulating levels of this hormone are associated with obesity." (PMID 34638645, 2021). "In this context, obesity is frequently associated with leptin resistance, a phenomenon traditionally attributed to impaired transport of this molecule through the blood–brain barrier that leads to increased leptin levels." (PMID 35010900, 2021). "The two LEP variants rs7799039 and rs11761556, which have been associated with obesity in Tunisia, were reported to be associated with breast cancer and systemic lupus erythematosus in Chinese and Mexican populations." (PMID 34131278, 2021). "Both central and peripheral OT treatments induce body weight loss in obese animal models with impaired leptin signaling, in diet-induced obesity rhesus monkeys and in obese humans." (PMID 34445256, 2021). "Mutations in the leptin gene and its regulatory regions can cause severe obesity and are linked to development of type 2 diabetes." (PMID 34444981, 2021). "Obesity, metabolic stress and T2DM are characterised by altered iron homeostasis: leptin-deficient ob/ob mice, that develop obesity and T2DM, show increased iron absorption and retention." (PMID 34831062, 2021). "While genetic leptin deficiency is rare, obesity-related leptin resistance is becoming increasingly common." (PMID 34502119, 2021). "Obesity can also develop as results of gene disruption or deficiency, such as the Brd2 gene and the leptin gene, both leading to metabolic pathways towards an obesity-related phenotype." (PMID 34944474, 2021). "Consistent with the fact that obesity is a strong risk factor for cancer, leptin is also a known promoter of tumor growth in breast cancer." (PMID 34094943, 2021). "The mechanisms that associate obesity and cancer as they relate to leptin are still elusive and, specifically, the pathological mechanisms of leptin to be associated with poor prognosis in cancer are still unclear." (PMID 34202969, 2021). "Further research is needed to confirm a causal link between obesity-induced leptin dysregulation and depression." (PMID 33546219, 2021). "Obesity and serum leptin are also a strong risk factors for Barrett’s esophagus, a precursor lesion in esophageal carcinoma." (PMID 34202969, 2021).
Obesity (continued). "Severe early-onset human obesity associated with mutations in genes encoding leptin or the leptin receptor are very rare and observed only in individuals homozygous for loss of function (LoF) mutations in those genes." (PMID 34045736, 2021). "Chronic low-grade systematic inflammation caused by obesity plays a significant role in obese OA, and the cytokine leptin mainly secreted by excessive adipose tissues in obese people is considered to be a causative link between obesity and OA." (PMID 34457118, 2021). "Leptin seems to play a role in obesity-associated cardiovascular risk through the activation of the sympathetic nervous system." (PMID 34675881, 2021). "Multiple epidemiological studies have investigated the association between circulating leptin and risks of obesity‐related cancers." (PMID 33038280, 2021). "Malnutrition, which is associated with reduced leptin levels, and obesity, which is associated with leptin resistance, increase the susceptibility to bacterial or viral respiratory infection, such as the H1N1 flu epidemic." (PMID 33907162, 2021). "LEP is a gene that encodes leptin, which is an important regulator of adipose tissue mass and obesity." (PMID 34094943, 2021). "Further investigation of metabolic marker expression, such as adiposity, insulin resistance, leptin, adiponectin, will be needed to elucidate how long-term sucrose consumption predisposes to obesity." (PMID 34163325, 2021). "Obesity is associated with overproduction of leptin, leading to leptin-induced local and peripheral inflammation via the activation of TNF-α and IL-6 production, and stimulation of surface markers." (PMID 34844584, 2021). "Together, these findings are in line with emerging evidence associating obesity with selective leptin resistance." (PMID 33925570, 2021). "Consistently, vascular injury mouse models of obesity and diabetes have demonstrated that leptin deficiency or leptin receptor signaling defects protect against neointimal hyperplasia." (PMID 34064112, 2021). "In fact, in a recent publication, a different expression level of the FTO gene, extensively described as linked to obesity, has been related to the concentration of hormones produced by the adipose tissue, being positively correlated with leptin." (PMID 35071145, 2021). "On the other hand, adiponectin reduction in obesity contributes to increased cardiovascular risk as its protective roles in atherogenesis oppose that of leptin." (PMID 33816341, 2021). "Several genes are known to be associated with monogenic types of obesity (e.g., LEP, LEPR, MC4R, and POMC); however, most cases of the disease are polygenic and are caused by an interaction of environmental, lifestyle, and genetic factors." (PMID 34834553, 2021). "Leptin has a close relationship with obesity-associated heart dysfunction; it can affect cardiac contractility in ventricular myocytes." (PMID 34557167, 2021). "The female BTBR ob/ob models with genetic deficiency of leptin have unmeasurable leptin levels, insulin resistance, obesity, and diabetes with glucose levels in the 300 mg/dL range." (PMID 34063911, 2021). "Despite the propensity for leptin to promote pathways involved in muscle regulation, its obesity-mediated upregulation is associated with resistance to its action." (PMID 33528828, 2021). "Fasting insulin levels at baseline were increased, and declined in seven out of eight patients during leptin substitution most likely reflecting a reduction in obesity-associated insulin resistance." (PMID 34002033, 2021). "Antibody development in patients with obesity or lipodystrophy was associated with higher leptin concentration, and higher antibody titers were associated with higher leptin concentration." (PMID 34084149, 2021). "In other studies, however, the leptin epigenetic profile was associated with obesity and increased risk of chronic diseases, mainly cancer in human and/or functional models." (PMID 34884678, 2021).
Obesity (continued). "The most well-known adipokine, leptin (encoded by the obese (ob) gene), was identified in 1994 as a metabolic link between obesity and OA." (PMID 33668426, 2021). "In the present study, the association between obesity indices (BMI, WC, and %BF), leptin and low‐grade inflammation (CRP, IL‐6, TNF‐α) in a Zanzibari population of individuals aged 5 years and above was investigated." (PMID 33680494, 2021). "The genetic leptin-deficient ob/ob mice and the leptin-resistant db/db mice are therefore widely used as animal models to study obesity and related metabolic disorders." (PMID 34183063, 2021). "Aberrant adipokine- and cytokine-mediated molecular signaling are the key features in obesity-associated breast cancer and leptin is one of the most important adipokines." (PMID 34970222, 2021). "SERPINF1 is a neurotrophic protein among the most abundant glycoproteins secreted by adipocytes and its genetic variants have been previously associated with obesity, insulin resistance, overall adiposity and circulating leptin levels." (PMID 34685777, 2021). "A short sleep duration results in lower leptin and elevated ghrelin levels, increasing the appetite and, thus, causing a vicious cycle with the progressing obesity." (PMID 32886313, 2021). "Mutations disrupting the leptin-melanocortin system have frequently been reported in severe, early-onset human obesity but the prevalence and extent of phenotypic impact of such mutations are unclear." (PMID 34045736, 2021). "Leptin is the first adipocyte-derived cytokine (adipokine), and its level increase in adipose tissue associated with obesity correlates with increases in serum leptin levels." (PMID 33708630, 2021). "To elucidate adaptive mechanisms of HPA axis components in various developmental stages and degrees of metabolic syndrome, we analyzed both young and old leptin-deficient ob/ob mice in a progressive obesity model." (PMID 33157254, 2021). "Leptin deficient (ob/ob) and LepR deficient (db/db) mice, carrying mutations in leptin (ob) and LepR (db) genes, respectively, exhibit excessive eating, develop obesity and diabetes, and are widely used as animal models of T2DM." (PMID 34795562, 2021). "Weight gain with accumulation of excess adipose tissue and obesity associate with elevated serum levels of leptin (hyperleptinaemia)." (PMID 34360982, 2021). "Two recent studies examined the potential role of leptin in obese asthmatics using analytical methods, which help elucidate the possible causal role of leptin in the association between obesity and asthma." (PMID 33418879, 2021). "In a second step, a quasi‐linear association of obesity indices with leptin, CRP, IL‐6, and TNF‐α was investigated." (PMID 33680494, 2021). "Our model underscores previous discoveries that genes that are critical for body weight regulation are mainly expressed in the hypothalamus and that mutated genes in monogenic forms of obesity play a key role in the leptin and melanocortin pathway." (PMID 34390703, 2021). "In the past 20 years, leptin has mainly been used in research and treatment of leptin deficiency-induced obesity and typical obesity." (PMID 34485124, 2021). "The observed association in the individual models between overweight/obesity and leptin is in agreement with previous studies." (PMID 33680494, 2021). "The female db/db models consisted of the deficient LepR with markedly elevated levels of leptin, insulin and leptin resistance, obesity and diabetes with levels of glucose around 500 mg/dL." (PMID 34063911, 2021). "Adipokines including leptin, adiponectin and resistin have been linked to risk of obesity-related cancers potentially through low-grade chronic inflammation pathways." (PMID 34876619, 2021). "Leptin can increase the risk of obesity related cancer, especially hormone dependent tumors, such as breast cancer, endometrial cancer and ovarian cancer." (PMID 34485124, 2021).
Obesity (continued). "Leptin, also known as obese (ob) gene, was discovered as the molecule that causes a mutated form of severe obesity in ob/ob mice." (PMID 33922961, 2021). "The current review attempts to provide an overview of recent in vivo and in vitro studies highlighting the involvement of leptin in pathogenesis of atherosclerotic complications associated with obesity and diabetes." (PMID 34064112, 2021). "Recent evidence shows that one of the major risk factors for the development of obesity is the inability of leptin to perform its metabolic functions of appetite suppression and promotion of energy expenditure." (PMID 34684432, 2021). "As it is well known, rodents with leptin signaling deficiency show a typical phenotype of fat accumulation and obesity." (PMID 34233759, 2021). "Enriori P.J., Evans A.E., Sinnayah P., Jobst E.E., Tonelli-Lemos L.,Billes S.K., Glavas M.M., Grayson B.E., Perello M., Nillni E.A.,Grove K.L., Cowley M.A. Diet-induced obesity causes severe butreversible leptin resistance in arcuate melanocortin neurons." (PMID 34782887, 2021). "Leptin or the obese (ob) gene was discovered in 1994 as a molecule that caused severe obesity in ob/ob mice." (PMID 34390703, 2021). "With this review, we aim to contribute to the understanding of leptin gene mutations as targets for obesity diagnostics and treatment strategies." (PMID 34504472, 2021). "Pathological single nucleotide variation (SNV) in the leptin gene, in the gene encoding the leptin receptor or a mutation located in the leptin-melanocortin pathway have been identified and shown to be at the origin of severe early-onset obesity." (PMID 33671490, 2021). "Among them, leptin and adiponectin are the most studied classic adipokines associated with obesity-triggered BC progression." (PMID 34350120, 2021). "We found that PrlhNTS neuron activation and Prlh overexpression in PrlhNTS cells abrogates AgRP neuron-driven hyperphagia and ameliorates the obesity of mice deficient in melanocortin signaling or leptin." (PMID 34462445, 2021). "Mutations in the POMC gene lead to severe human obesity while rodent Pomc knockouts are obese and less sensitive to leptin." (PMID 34955895, 2021). "Leptin deficiency and mutations in the leptin receptor are recognized rare causes of monogenic early onset, severe obesity, and recombinant leptin replacement therapy produces significant clinical benefit in these patients." (PMID 33777773, 2021). "Although leptin is seen as an anorexigenic hormone, increased levels of leptin in obesity have previously been associated with more activity in the motivation/reward circuitry while looking at food pictures." (PMID 34768651, 2021). "The combined therapy of leptin and pramlintide (an amylin analog) results in more weight loss in subjects with obesity than either treatment alone." (PMID 34084149, 2021). "Some studies indicated that the G allele of the LEP rs7799039 was associated with higher anthropometric measurements and increased risk of obesity." (PMID 34205732, 2021). "That is one of the reasons that leptin deficiency leads to high food intake and, consequently, to obesity." (PMID 35011070, 2021). "The role of leptin in obesity was initially thought to be an anti-obesity hormone, but this role is usually reduced by LR, which is one of the causes of obesity." (PMID 34039404, 2021). "Obesity is associated with abundant circulating leptin; however, it stimulates numerous cellular processes that attenuate sensitivity to leptin leading to development of a metabolic disorder, known as leptin resistance." (PMID 33827616, 2021). "Satiety is regulated by endocrine factors including leptin, and impaired leptin signaling is associated with obesity." (PMID 33810547, 2021). "Higher amount of leptin and ghrelin cause permanent damage on hypothalamic function ultimately causing hyperphagia and obesity in offspring." (PMID 34368253, 2021).
Obesity (continued). "In fact, human obesity is associated with decreased adiponectin and elevated leptin levels, the latter resulting from an increased release by the expanding fat mass." (PMID 33572989, 2021). "Adiposity, obesity, and obesity-related inflammatory factors such as leptin and interleukin-6 were found to be associated with RNFL thinning in children affecting all except the temporal quadrant." (PMID 33630879, 2021). "These high leptin levels in these SARS-CoV-2 patients correlated with their BMI suggesting that obesity was the underlying cause of the observed high leptin levels and thus of the more serious presentation of the COVID-19 disease." (PMID 33824998, 2021). "Loss-of-function mutations in the leptin gene cause obesity in ob/ob mice and also, rare cases of human obesity with severe early onset and hyperphagia." (PMID 34390703, 2021). "Although they were considered simultaneously, obesity indices (BMI and %BF), were significantly associated with high levels of leptin (third and fourth quartiles) and WC only in the fourth quartile (model 5)." (PMID 33680494, 2021). "Another cellular process that critically contributes to hypothalamic leptin resistance and is heavily linked to the IKKβ/NF-kB pathway in diet-induced obesity is ER stress." (PMID 33741533, 2021). "In the obese context, leptin has been linked to tumor-initiating cell survival and obesity-associated triple negative breast cancer development by promoting cancer stem cell enrichment and epithelial-to-mesenchymal transition (EMT)." (PMID 33987528, 2021). "We considered the possibility that the downregulated expression of exons II and III in ob/ob mice was caused by obesity, which cannot be normalized by acute leptin treatment." (PMID 33106599, 2021). "This study contributes to the general understanding on the association between obesity—measured as fat mass—, leptin and low‐grade inflammation in the sub‐Saharan African population." (PMID 33680494, 2021). "Chronically high leptin levels in obesity result in decreased sensitivity and loss of appetite inhibition." (PMID 34768715, 2021). "Elevated leptin levels, in combination with the obesity-induced pro-inflammatory state, further increases the risk for the development of a disproportionate or hyper-inflammatory response upon SARS-CoV-2 infection." (PMID 33920604, 2021). "Leptin deficiency or resistance in human patients causes severe obesity, diabetes, and infertility with hypogonadism." (PMID 33673730, 2021). "In particular, a large variety of genetic models, including leptin-deficient Ob/Ob mice, or obese Zucker rats, have been crucial to reveal some of the molecular and cellular signatures involved in obesity." (PMID 33574566, 2021). "Leptin is an obesity-associated adipokine that is known to regulate energy metabolism and reproduction and to control appetite via the leptin receptor." (PMID 33799880, 2021). "Leptin is associated with obesity and mesangial cells obtained from wild-type mice display enhanced TSP1, fibronectin, collagen IV and TGF-β expression following leptin-treatment." (PMID 33920030, 2021). "Moderate-load exercise can effectively reduce the inflammatory response caused by obesity, improve leptin resistance, increase serum testosterone levels in men and rats/mice, and improve the quality of sperm." (PMID 33472656, 2021). "The let-7 family is involved in adipocyte differentiation by targeting the high-mobility group AT-Hook 2 (HMGA2) protein, which reduces adipose tissue in obese leptin-deficient mice, suggesting, once again, a role for leptin and obesity in CRC." (PMID 34199293, 2021). "Its use in obesity treatment has been considered to help normalize decreased leptin levels caused by weight loss." (PMID 34444990, 2021). "Obesity is also associated with leptin resistance, which affects leptin signaling and its downstream physiological effects." (PMID 33557185, 2021).